MIR639 (microRNA 639)
Synonyms: hsa-mir-639; MIRN639
Gene: MicroRNA gene on chromosome 19 (14,529,543 to 14,529,640, forward strand). Ensembl gene ENSG00000283822.
Gene Ontology:
Biological process: miRNA-mediated post-transcriptional gene silencing